EGFR (epidermal growth factor receptor)
Diseases named in the same sentence as EGFR in open-access papers (continued):
Sharing a sentence is not in itself a finding about the gene and the disease.
breast carcinoma (continued). "EGFR appears to be involved in the regulation of post-translational PD-L1 expression, and EGFR stimulation was shown to stabilize PD-L1 in breast cancer cells via glycosylation." (PMID 36531159, 2022). "This study focuses on the expression and distribution of EGFR and c-Met in breast cancer as well as the related metabolic pathways and molecular mechanisms associated with different CD82 palmitoylation site mutations." (PMID 35538033, 2022). "For example, EGFR-amplified BM from NSCLC shows similar oncogenic changes with EGFR-amplified classic glioblastoma and Her2+ breast cancer BM." (PMID 35251014, 2022). "For example, patients with BCR-ABL leukemias, HER2-overexpressing breast cancers, or EGFR-driven lung cancers benefit immensely from kinase-targeted therapies (often as adjuvants to chemotherapy, radiation, and/or surgery)." (PMID 35879309, 2022). "Previous studies reported that three target molecules, PDL1, uPAR, and EGFR, were highly expressed in human breast cancer cells." (PMID 35335849, 2022). "Clinical and experimental studies have shown that EGFR/ErbB1 inhibitors can relieve neuropathic and breast cancer-related pain." (PMID 35909446, 2022). "Here we used two HER2-positive breast cancer cell lines, BT474 and SKBR3, to further understand the molecular mechanism underlying trastuzumab action in terms of EGFR and HER2 heterodimers." (PMID 36552857, 2022). "Ivermectin can reverse chemotherapy resistance in colorectal cancer and breast cancer cells by regulating the EGFR/ERK/Akt/NF-κB pathway." (PMID 36100894, 2022). "For example, cross-talk between integrin α6β4 and epidermal growth factor receptor (EGFR) promotes breast cancer progression by inducing EGFR clustering and Rho activation." (PMID 35835740, 2022). "It was illustrated that the close relationship between tumour‐derived MVs and epidermal growth factor receptor (EGFR) signalling in glioblastoma and breast cancer." (PMID 36448260, 2022). "Downregulation of AKT1 in mechanistic experiments dephosphorylate PIKfyve on Ser and inactivate the PIKfyve site, resulting in mammary cancer metastasis through EGFR signaling pathways." (PMID 35341150, 2022). "As EGFR is a potential therapeutic target for TNBC, EGFR-specific CAR NK cells (EGFR-CAR NK cells) is a promising strategy to inhibit tumor growth in breast cancer cell line-derived xenograft (CLDX) and patient-derived xenograft (PDX) mouse models." (PMID 35111680, 2021). "Tumor suppression functions of Tid1 rely on degradation of ErbB2 in breast cancer, and attenuation of EGFR/Akt/Erk signaling in HNSCC and in NSCLC." (PMID 33406664, 2021). "PI3K inhibitor (BEZ235, AEW541), mTOR inhibitor (RAD001), and EGFR/HER2 inhibitor (lapatinib) suppress proliferation of letrozole-resistant breast cancer cells." (PMID 33477469, 2021). "Taken together, these results suggest that EGFR and HER2 expressions are strongly associated with Pim1 expression and the sensitivity to Pim1 inhibitors in breast cancer cells." (PMID 34267653, 2021). "Treatment of HER2-positive breast cancer with the HER2/EGFR inhibitor lapatinib leads to decreased FOXM1 expression, suggesting that HER2 positively regulates FOXM1." (PMID 33920089, 2021). "Taken together, these data suggest that HOIP inhibitor also inhibits EGFR-mediated NF-κB activation in breast cancer cells and suppresses breast cancer cell proliferation and clonogenicity." (PMID 34769306, 2021).
breast carcinoma (continued). "Taken together, these data indicate that alterations in the level of pY374-PKCδ, regulated by the opposing actions of the tyrosine kinase FER and the tyrosine phosphatase PTPN14, modulate EGFR signaling and the growth of breast cancer cells." (PMID 33411917, 2021). "The notion is supported our expression analysis using METABRIC database because the correlation between RhoB mRNA expression and prognosis of HER2-positive breast cancer patients were reversed dependent on expression level of EGFR mRNA." (PMID 34187934, 2021). "Reportedly, mediator complex subunit 19 (Med19) interacts with EGFR and increases its expression; it activates the EGFR/MEK/ERK pathway and exerts its oncogenic activity in an EGFR-dependent manner in breast cancer." (PMID 33909822, 2021). "In a similar study, let-7a containing exosomes with a surface expressed target peptide efficiently delivered cargo to epidermal growth factor receptor (EGFR) expressing breast cancer cells." (PMID 33800282, 2021). "It has been reported that AT1R transactivates the EGFR in prostate and breast cancer cells, resulting in ERK, STAT3, and PKC phosphorylation." (PMID 34943797, 2021). "Here we demonstrate that we can train a neural network using the motions of EGFR from six breast cancer cell lines and reach 83% accuracy in classifying these cells." (PMID 34390568, 2021). "In breast cancer cells, TiO2 NPs inactivated EGFR to inhibit activation of the downstream signaling pathway AKT and ERK, reducing cell adhesion and facilitating cell apoptosis." (PMID 33534781, 2021). "AURKA attenuates the efficacy of inhibition of the PI3K-AKT-mTOR pathway, a downstream pathway of EGFR, in breast cancer." (PMID 33451333, 2021). "Bioengineered exosomes with a transmembrane domain fused with the GE11 peptide delivered the let-7a miRNA to EGFR-expressing xenograft breast cancer tissue in immunodeficient mice, leading to an anti-tumor effect." (PMID 34677212, 2021). "SHP-1 expression was associated with better survival in patients with breast cancer, whereas SHP-1 expression was negatively correlated with EGFR in human breast cancer." (PMID 34591414, 2021). "We first acquired EGFR motions from six breast cancer cell lines which have different gene expression profiles, hormone receptor status and surface receptor status: MCF7, BT474, SKBR3, MDA-MB-468, MDA-MB-231 and BT549." (PMID 34390568, 2021). "Nuclear EGFR correlates with poor outcomes in multiple human malignancies, including breast cancer, ovarian cancer, non-small cell lung cancer (NSCLC), and oropharyngeal squamous carcinoma." (PMID 34741044, 2021). "For example, exosomes can effectively deliver microRNAs (miRNAs) to breast cancer cells expressing epidermal growth factor receptor (EGFR)." (PMID 34295338, 2021). "Data from Hatton and colleagues indicated that EGFR expression levels in human breast cancer cells were related to PLD2 expression and its enzymatic reaction product PA." (PMID 33832505, 2021). "There was a report of combining flavopiridol and HER-2 targeting Trastuzumab that resulted in enhanced apoptosis and decreased EGFR expression in breast cancer." (PMID 34621175, 2021). "A previous study showed that the nuclear interaction of Stat3 and EGFR occurs when the iNOS/NO pathway is activated in breast cancer." (PMID 34884765, 2021). "Accordingly, our results with the Rac inhibitors EHop-016 and MBQ-167 show that both these inhibitors significantly reduce the MFE of HER2+ and EGFR+ breast cancer cells." (PMID 34074257, 2021). "HER2-positive breast cancer cells usually contain homo- or heterodimers of EGFR members, such as HER2/HER2 or HER2/HER336–38." (PMID 33875644, 2021). "We observed that ribociclib-induced senescent breast cancer cells are tolerant to a large number of compounds, with viability being maintained by EGFR activation." (PMID 34944934, 2021).
breast carcinoma (continued). "The activation of EGFR leads to an increase in the downstream activity of caspase 8 and 9, which leads to the apoptosis of breast cancer cells." (PMID 34950031, 2021). "In this review we highlight the crosstalk between downstream signaling cascades activated by PRLR and EGFR/HER2 in breast cancer and discuss how these receptors work together to affect breast cancer behavior and promote cancer progression." (PMID 34572912, 2021). "The cancer-centric cluster of the amplified oncogenes indicated that ERBB2/EGFR/AKT is predominately found in breast cancer." (PMID 34535639, 2021). "It is known that breast cancers with high EGFR expression are more aggressive, larger in size and more capable to metastasize to the lymph nodes and brain." (PMID 34404439, 2021). "Here, using the Drosophila intestine and human lung and breast cancer cell lines we uncover an important role of RAL GTPases activating EGFR/MAPK signalling-driven cell proliferation through induction of EGFR internalisation." (PMID 34096503, 2021). "This cell line is an established model for HER2 overexpressing breast cancer, and has on average 4-fold lower EGFR-, and ~50-fold higher HER2 expression levels than normal breast tissue." (PMID 34831465, 2021). "Despite the promising results in pre-clinical settings, published reports indicate that cetuximab therapy did not yield favorable outcome in large clinical trials of metastatic EGFR expressing breast cancers." (PMID 33804477, 2021). "A crosstalk between RANK and EGFR signaling has been described in the context of osteoclast differentiation, as well as in breast cancer for a particular RANK truncated isoform." (PMID 33785053, 2021). "On the other hand, that upregulated expression of EGFR protein has been reported to occur in 16%–36% of breast cancers." (PMID 33907495, 2021). "This role of RAL proteins impacts stem cell proliferation and regeneration of the intestinal epithelium and has implications in pathological settings that depend on active EGFR signalling, including intestinal hyperplasia and breast cancer cell growth." (PMID 34096503, 2021). "There have also been many reports on various coumarin-containing compounds entering possible interaction with tyrosine kinase receptors in different carcinomas, for example, breast carcinoma that expresses EGFR." (PMID 34007407, 2021). "Recently, Hox genes have been shown to transcriptionally activate EGFR in drosophila and breast cancer cells, although their role in EGFR-driven lung tumors is largely uncharacterized." (PMID 34344431, 2021). "In this study, JAC1 was identified to degrade the overexpressed HER2 and other EGFR members in breast cancer cells." (PMID 33875644, 2021). "Shi and colleagues managed to develop an exosome platform entitled synthetic multivalent antibodies retargeted exosome (SMART-Exo) to provide dual antibodies against CD3 (T-cells) and human epidermal growth factor receptor 2 (HER2) or EGFR in breast cancer." (PMID 34203051, 2021). "The gene expression of EGFR in a series of breast cancer cell lines was assessed using a publicly available microarray dataset (GSE41313) and Western blotting." (PMID 34879870, 2021). "Taken together, it is likely that the regulation of EGFR phosphorylation through PTPRH activation and RhoB degradation by the CUL3/KCTD10 E3 complex is conserved in HER2/EGFR-double positive breast cancer cells." (PMID 34187934, 2021). "HER2, DDR1/2, and EGFR are receptor tyrosine kinases which are frequently upregulated in breast cancer and are activated by various ligands e.g., heregulin, collagens, or EGF, respectively." (PMID 33670586, 2021). "Priorly, miRNA-loaded Exo was targeted to epidermal growth factor receptor (EGFR)-expressing breast cancer cells." (PMID 34099630, 2021).
breast carcinoma (continued). "We recently reported that MICAL2 potentiates breast cancer cell migration via maintaining epithelial growth factor receptor (EGFR) stability, leading to the activation of the P38/HSP27/actin pathway downstream of EGFR." (PMID 33842533, 2021). "LAS preferentially induced the EGFR pathway in breast cancer cells (MCF-7) via exogenous and endogenous caspase-dependent apoptosis." (PMID 34950031, 2021). "Herein, we demonstrate the potential for Rac inhibitors as targeted therapeutics for EGFR/HER2 therapy resistant breast cancer." (PMID 34074257, 2021). "EGFR is often used as the canonical ErbB, and ErbB2 is also widely studied due to its connection to breast cancer." (PMID 34827688, 2021). "Remarkably, through the miR-338-3p/EYA2 pathway, EGFR increased breast cancer cell growth, EMT, migration, invasion, and metastasis in an allograft tumor mouse model." (PMID 34206026, 2021). "Primaquine and CQ induce the apoptosis of breast cancer through nEGFR/Stat3-dependent c-Myc downregulation, which provides a strategy for the treatment of breast cancer by targeting the EGFR signaling components." (PMID 34884765, 2021). "TINCR was found to be upregulated and positively correlated with EGFR expression in human breast cancer." (PMID 33446634, 2021). "Its role in the tamoxifen response and cell metabolism in ER+ breast cancer cells is promoted by the miR-186-3p/EREG/EGFR axis." (PMID 34359587, 2021). "HER2 is often amplified in HER2-enriched breast cancer whereas decreased PTEN and increased EGFR expression is associated with TNBC." (PMID 34298660, 2021). "Different types of breast cancer are typically classified based upon expression of estrogen receptor, progesterone receptor, and epidermal growth factor receptor." (PMID 34439373, 2021). "Tamoxifen-resistant breast cancer cells (LTam) showed an hyperactivation of the HER/EGFR/Akt/ERK pathway." (PMID 33477469, 2021). "In prostate and breast cancers, AR activation can be achieved also by a ligand-independent signaling through receptor tyrosine kinases such as epidermal growth factor receptor (EGFR)." (PMID 34681618, 2021). "Neratinib is a dual HER2/EGFR tyrosine kinase inhibitor that was recently approved by the FDA for treatment of advanced or metastatic HER2-positive breast cancer." (PMID 33420373, 2021). "As a consequence of its capability to trigger the epidermal growth factor receptor (EGFR) pathway by shedding EGFR ligands, ADAM17 activity is associated with cancer progression of several malignancies, including colon and breast cancer." (PMID 33579029, 2021). "The high expression of PTPRH mRNA was significantly correlated with high EGFR mRNA expression in 13 HER2-positive breast cancer cell lines, suggesting the functional significance of PTPRH in the dephosphorylation of EGFR in HER2-positive breast cancer cells." (PMID 34187934, 2021). "For about 30% of the patients, BM resulting from some lung and breast cancers, as well as the primary cancer cells themselves, exhibit an overexpression of the epidermal growth factor receptor (EGFR) and HER2." (PMID 34504791, 2021). "It has been reported that quercetin potently suppresses the autophosphorylation of the EGFR in human colon carcinoma cell, and quercetin induces apoptosis via inhibition of EGFR in breast cancer cell lines." (PMID 35069207, 2021). "While CAPE has mostly been found effective against breast cancer and nasopharyngeal carcinoma cells via targeting EGFR, it showed dose dependent inhibition of both the total and phosphorylated forms of EGFR protein expression (0–40 μM)." (PMID 33530424, 2021). "Breast cancer cell treatment with an EP4 agonist or synthetic PGE2 both stimulated epidermal growth factor receptor (EGFR) and increased tumor spheroid invadopodia, invasion, and extracellular matrix degradation by breast cancer cells." (PMID 35127497, 2021).
breast carcinoma (continued). "Pyrotinib (or SHR1258) is an irreversible inhibitor of EGFR/HER1, HER2, and HER4 shown to suppress tumor growth in HER2-positive breast cancer xenograft mouse models, which was associated with a favorable safety profile." (PMID 34208071, 2021). "These epidermal growth factor receptor (EGFR) family members are commonly targeted in breast cancer therapies by antibodies and/or small inhibitors that disrupt different cellular pathways." (PMID 34437486, 2021). "We thus examined if the expression level of RhoB correlates with the prognosis of human HER2/EGFR-double positive breast cancer patients using the Molecular Taxonomy of Breast Cancer International Consortium (METABRIC) database." (PMID 34187934, 2021). "In TAM-embedded breast cancer BT-20 spheroids with high EGFR density, treatment with cetuximab-targeted gold nanorods (CTX-AuNR) plus NIR irradiation enhanced ROS generation, induced cytotoxicity, and reprogrammed TAMs to the anti-tumor M1 phenotype." (PMID 34209679, 2021). "In PC-3 prostate cancer, metastatic breast cancer MCF-7 cells and lung cancer cell lines, JWH-015 had anti-proliferative action; moreover, it inhibited the activation of EGFR in ERα breast cancer cells." (PMID 34943903, 2021). "In this context it is unsurprising that expression of other regulator of EGFR endocytosis, such as Rab5, are markers of poor prognosis and lymph node metastasis in breast cancers." (PMID 34556814, 2021). "In this review, we have provided ample evidence to support the significant role for PRLR and EGFR/HER2 signaling crosstalk in breast cancer." (PMID 34572912, 2021). "Trastuzumab precipitated endogenous RANK demonstrating that the two receptors physically interact in breast cancer cells in an EGFR-independent manner." (PMID 33785053, 2021). "Lapatinib in combination with foretinib, an inhibitor of hepatocyte growth factor receptor, was also found to inhibit migration in triple-negative human breast cancer cell lines due to its action on EGFR." (PMID 34204236, 2021). "The CD99 molecule has previously been linked to Rho GTPase activity, actin dynamics and growth factor signalling in breast cancer; EGFR stimulates RhoA and Rac1 activity and actin reorganization, and these pathways are antagonised by CD99-mediated signalling." (PMID 34374417, 2021). "Dysregulation of EGFR expression and signaling was previously well documented to contribute to the progression and metastasis of breast cancer while MSANTD2 played a crucial role in decreased epidermal growth factor endocytosis." (PMID 34627275, 2021). "CD73 promotes metastasis of breast cancer via the expression of EGFR and IL-8, while, CD73 blockade restrains melanoma metastasis through the formation of IL-1β and TNF-α." (PMID 32902664, 2021). "Many EGFR TKIs are explored as efficient therapeutics for breast cancer, NSCLC or gastric cancer, however, only a few of them are further investigated in bladder cancer." (PMID 35004854, 2021). "SGCE promotes breast cancer stem cell self-renewal, chemoresistance, and metastasis both in vitro and in vivo by stabilizing EGFR." (PMID 34827136, 2021). "Breast cancer cells overexpress EGFR, and EGFR has two functions: membrane-bound signaling and nuclear signaling." (PMID 34884765, 2021). "In EGFR-overexpressing MDA-MB-468 breast cancer cells, the combined use of cetuximab and matuzumab (anti-EGFR mAbs) decreased growth and survival to a greater extent than the use of a single Ab treatment." (PMID 34575943, 2021).